SLC45A4 (solute carrier family 45 member 4)
Description:
Neuronal polyamine-transporter involved in pain perception. Transports polyamines such as putrescine, cadaverine, spermine and spermidine. Expressed in sensory neuron subtypes within the dorsal root ganglion, where it regulates the excitability of C-polymodal nociceptors by mediating polyamine transport (By similarity).
Synonyms: KIAA1126
Tractability: Antibody: UniProt predicts a signal peptide or a membrane-spanning region; the Human Protein Atlas places it where antibodies can reach. PROTAC: ubiquitination databases record sites on it.
Gene: Protein-coding gene on chromosome 8 (141,207,166 to 141,308,318, reverse strand). Ensembl gene ENSG00000022567.
Subcellular location: Cell membrane
Subcellular location (Human Protein Atlas): Plasma membrane
Gene Ontology:
Molecular function: polyamine transmembrane transporter activity; protein binding; putrescine transmembrane transporter activity; spermidine transmembrane transporter activity; spermine transmembrane transporter activity; sucrose:proton symporter activity; transmembrane transporter activity
Biological process: sensory perception of pain; sucrose transport; polyamine transmembrane transport; putrescine transport; spermidine transmembrane transport; spermine transmembrane transport; transmembrane transport
Cellular component: plasma membrane
Genetic constraint (gnomAD): Loss-of-function variants: 32 observed, 62.84 expected, observed/expected ratio (o/e) 0.51, 90% interval 0.38 to 0.68. The upper end of that interval is the gene's LOEUF score, 0.68, which puts it in group 2 of 6, group 1 being the genes least tolerant of losing a copy. Missense variants: 1,027 observed, 1,166.8 expected, observed/expected ratio (o/e) 0.88, 90% interval 0.83 to 0.93. Synonymous variants: 535 observed, 507.52 expected, observed/expected ratio (o/e) 1.05, 90% interval 0.98 to 1.13.
Homologues: Orthologues: chimpanzee SLC45A4 (99% identical), macaque SLC45A4 (96% identical), dog SLC45A4 (84% identical), guinea pig Slc45a4 (82% identical), pig SLC45A4 (82% identical), mouse Slc45a4 (82% identical), rat Slc45a4 (81% identical), rabbit SLC45A4 (80% identical), tropical clawed frog slc45a4 (74% identical), zebrafish slc45a4b (56% identical), zebrafish SLC45A4 (47% identical), Drosophila melanogaster lovit (23% identical), and 1 more. Paralogues in human: SLC45A1 (31% identical), SLC45A2 (24% identical), SLC45A3 (17% identical).
Diseases named in the same sentence as SLC45A4 in open-access papers:
SLC45A4 is named in the same sentence as 5 diseases in open-access papers, as found by Europe PMC text mining. Sharing a sentence is not in itself a finding about the gene and the disease. The quoted sentences say what the papers report.
pancreatic ductal adenocarcinoma (2 papers, 2021 to 2022). An infiltrating adenocarcinoma that arises from the epithelial cells of the pancreas. "SLC45A4 was found to be overexpressed in pancreatic ductal adenocarcinoma (PDA) and was strongly linked to poor overall survival in PDA patients." (PMID 35518353, 2022).
atherosclerosis (1 paper, 2021). A disease characterized by the build-up of fatty material and calcium deposition in the arterial wall resulting in partial or complete occlusion of the arterial lumen. "Whether the rest of them, including Dkk2, Ltbp2, Lamb1, Cdca7l, Dclk1, and Slc45a4, are associated with atherosclerosis and d-flow has not been reported." (PMID 34282126, 2021).
osteosarcoma (1 paper, 2022). A usually aggressive malignant bone-forming mesenchymal neoplasm, predominantly affecting adolescents and young adults. "The expression of SLC45A4 was higher in low-risk group and higher expression of SLC45A4 was associated with a better clinical outcome, so SLC45A4 might be a tumor suppressor gene in osteosarcoma." (PMID 35518353, 2022). "Thus, SLC45A4 may act as both an oncogene and a tumor suppressor in various types of tumors, and its involvement in osteosarcoma has to be investigated further." (PMID 35518353, 2022).
cancer (4 papers, 2020 to 2025). A tumor composed of atypical neoplastic, often pleomorphic cells that invade other tissues. "In mammalian cells, SLC45A4 was implicated in different types of cancers and associated with different clinical outcomes regarding the type of cancer." (PMID 41266324, 2025). "SLC45A4 is mostly described as a biomarker of the clinical severity of cancer, but its mechanisms are poorly understood." (PMID 41266324, 2025). "We investigated the gene expression of SLC45 family members in TCGA datasets from the GEPIA web server, which showed that SLC45 family members, especially SLC45A4, were overexpressed in many types of cancer." (PMID 34010493, 2021). "In this study, we discovered that SLC45A4 promotes GABA de novo synthesis in human cancer cells." (PMID 41266324, 2025). "As the proton‐gradient exists across the plasma membrane, SLC45A4 may provide glucose to cancer cells more efficiently than SLC2 family and SLC5 family." (PMID 34010493, 2021). "One of them, SLC45A4, is a proton-associated sucrose transporter, for which there are no reports of direct association with cancer or cell survival (PubMed search on 08-Jan-2021)." (PMID 33589614, 2021).
Tumor (2 papers, 2021 to 2022). "Overexpression of SLC45A4 is associated with tumor progression and the poor prognosis of PDA patients." (PMID 34010493, 2021). "Tumor growth and weight in the SLC45A4 silencing group were repressed." (PMID 34010493, 2021).